MUTYH (mutY DNA glycosylase)
Diseases named in the same sentence as MUTYH in open-access papers (continued):
Sharing a sentence is not in itself a finding about the gene and the disease.
familial adenomatous polyposis 2 (6 papers, 2018 to 2024). "PVs/LPVs in MUTYH are associated with autosomal recessive colorectal adenomatous polyposis, but interestingly, monoallelic variants on this gene have been reported by both our and other groups as being associated with cancer predisposition in several patients." (PMID 38136276, 2023). "Biallelic MUTYH mutations are involved in the pathogenesis of a form of autosomal recessive colorectal adenomatous polyposis (MUTYH-associated polyposis syndrome, MAP)." (PMID 34026625, 2021).
colorectal tumors (5 papers, 2015 to 2024). "Due to the critical role MUTYH plays in base excision repair, DNA with functional loss of MUTYH leads to an excess of 8-oxoguanine (8-oxo-G) which results in inappropriate G:C > T:A transversions in MAP colorectal tumors." (PMID 33419231, 2021). "In conclusion, common colorectal tumour risk alleles contribute to the development of multiple adenomas in patients without pathogenic germline APC or MUTYH variants." (PMID 24801760, 2015). "Somatic G → T mutations in the APC and KRAS genes are frequently observed in such colorectal tumors in MAP patients, and even in non-MAP patients, reduced MUTYH expression is associated with an increased number of somatic G → T mutations in prostate adenocarcinoma." (PMID 29098062, 2017).
Wilson disease (5 papers, 2020 to 2025). A very rare inherited multisystemic disease presenting non-specific neurological, hepatic, psychiatric or osseo-muscular manifestations due to excessive copper deposition in the body. "Additionally, we observed a high frequency of GPPs with P and LP variants associated with Malignant hyperthermia (8.7%), MUTYH-associated polyposis (8.5%), and Wilson’s disease (8.3%)." (PMID 39020067, 2024). "P/LP variants were identified in MUTYH (14 individuals) and ATP7B (5 individuals), known to cause MUTYH‐Associated Polyposis and Wilson disease respectively when present in the compound heterozygous or homozygous state." (PMID 40970488, 2025).
adrenocortical carcinoma (4 papers, 2019 to 2025). "The origin of this signature in BC remains to be established, but it has recently been associated with germline mutation in the repair enzyme MUTYH in colorectal and adrenocortical carcinomas." (PMID 30653559, 2019). "The copy‐neutral LOH and whole‐genome doubling in our patient resemble the pattern observed in adrenocortical carcinoma, which has been reported as the most frequent cancer in heterozygous MUTYH carriers and points to a possible role for MUTYH in the pathogenesis of this PC case." (PMID 36808802, 2023).
bladder cancer (4 papers, 2016 to 2024). "Here we aimed to assess the associations of nineteen polymorphisms from seven DNA repair–associated genes (PRAP1, OGG1, APEX1, MUTYH, XRCC1, XRCC2 and XRCC3) with bladder cancer and their interactions in the disease in a Han Chinese population." (PMID 27153553, 2016).
esophageal cancer (4 papers, 2021 to 2025). A primary or metastatic malignant neoplasm involving the esophagus. "The expression of pivotal BER gene MutY homolog (MUTYH) was found to be significantly downregulated in an esophageal cancer cell line with cisplatin resistance." (PMID 34766149, 2021).
Fanconi anemia (4 papers, 2018 to 2025). Fanconi anemia (FA) is a hereditary DNA repair disorder characterized by progressive pancytopenia with bone marrow failure, variable congenital malformations and predisposition to develop hematological or solid tumors. "Since the detection rate of biallelic pathogenic variants is extremely low, including ataxia telangiectasia for ATM and Fanconi anemia for BRCA1 and BRCA2, we did not describe the autosomal recessive mode of inheritance in the Fact Sheet, except for MUTYH." (PMID 40183848, 2025).
Li-Fraumeni syndrome (4 papers, 2018 to 2023).
lymphoma (4 papers, 2013 to 2025). A malignant (clonal) proliferation of B- lymphocytes or T- lymphocytes which involves the lymph nodes, bone marrow and/or extranodal sites. "MUTYH inactivation in mice is associated with small intestinal tumour and/or lymphomas, either spontaneous or induced by KBrO3 exposure." (PMID 26109431, 2015). "This suggested that presence of a MUTYH deficiency is sufficient to predispose for malignancies of the intestinal tract, such as lymphoma and adenoma." (PMID 23450852, 2013).
neuroblastoma (4 papers, 2020 to 2024). Neuroblastoma (NB) is the most common solid, extracranial childhood tumor. "While aberrant homologous recombination showed similar contributions to mutagenesis across pediatric and adult tumors, signatures of MUTYH-related base excision repair deficiency were enriched in pediatric soft-tissue sarcoma and neuroblastoma." (PMID 38755180, 2024). "Most neuroblastoma tumors show heterozygous loss instead of homozygous loss of OGG1 or MUTYH, which we expect to result in a similar but more modest phenotype." (PMID 34479993, 2021). "Other neuroblastoma tumors indicate that partial loss of OGG1 or MUTYH can also be sufficient to induce high C > A substitution levels." (PMID 34479993, 2021). "We identified a high contribution of C > A mutational signatures 18 and 36 in the OGG1 and MUTYH knockout clones, respectively, which cluster together with neuroblastoma tumors with OGG1 or MUTYH CNL." (PMID 34479993, 2021). "Overall, these results indicate that the OGG1 and MUTYH knockout clones have a high contribution of C > A mutational signatures 18 and 36, respectively, and cluster together with neuroblastoma tumors with OGG1 or MUTYH CNL." (PMID 34479993, 2021). "We show that neuroblastoma tumors with high C > A substitution frequencies were enriched for copy number loss (CNL) of OGG1 and MUTYH." (PMID 34479993, 2021). "To show that the increased levels of 8-oxoG are indeed caused by the defects in OGG1 and MUTYH, we performed rescue experiments by inducing overexpression of wild-type OGG1 or MUTYH in neuroblastoma cell lines with CNL of OGG1 or MUTYH, respectively." (PMID 34479993, 2021). "CNL of MUTYH or OGG1 is common in neuroblastoma since these genes are located on chromosome arms 1p and 3p, respectively, which are recurrently lost in neuroblastoma." (PMID 34479993, 2021). "In concordance, knockout of OGG1 and MUTYH results in increased accumulation of C > A substitutions in a neuroblastoma cell line." (PMID 34479993, 2021). "Overall, these results indicate that 8-oxoG levels are increased in neuroblastoma organoids and cell lines with defects in MUTYH and OGG1 and that this can be rescued by overexpression of the affected wild-type gene." (PMID 34479993, 2021). "In clustering analysis, these clones group together with neuroblastoma tumors with OGG1 or MUTYH CNL." (PMID 34479993, 2021). "Therefore, we analyzed WGS data of our neuroblastoma cohort for CNL and mutation status of MUTYH, OGG1, and NUDT1." (PMID 34479993, 2021). "In our cohort of neuroblastoma, signature 18 was also identified as a common signature in a cluster of tumors with frequent CNL of OGG1 or MUTYH (>60% of the tumors)." (PMID 34479993, 2021). "To validate the correlation between C > A substitutions and defects in the 8-oxoG pathway, we created CRISPR-Cas9 knockout clones of MUTYH, OGG1, or NUDT1 in a neuroblastoma cell line (CHP134)." (PMID 34479993, 2021). "We used CRISPR-Cas9 genome editing to create knockout clones of MUTYH and OGG1 in neuroblastoma cells." (PMID 34479993, 2021). "However, we could not find any germline mutation in the MUTYH coding region in our neuroblastoma dataset." (PMID 33168834, 2020).
Parkinson disease (4 papers, 2015 to 2022). A progressive degenerative disorder of the central nervous system characterized by loss of dopamine producing neurons in the substantia nigra and the presence of Lewy bodies in the substantia nigra and locus coeruleus. "MUTYH is implicated in cancer, inflammation and Parkinson disease." (PMID 25889687, 2015). "MUTYH has been suggested to actively contribute to the neurodegenerative process in Parkinson's diseases and Huntington disease." (PMID 34970419, 2021).
serrated polyposis (4 papers, 2008 to 2025). "In approximately 1% of patients with serrated polyposis, biallelic mutation of MUTYH can be demonstrated." (PMID 21660283, 2011). "The genetic basis for serrated polyposis is yet to be determined, though small numbers of patients have reported mutations in MUTYH, PTEN, and EPHB2." (PMID 21660283, 2011). "Conversely, when biallelic MUTYH mutation carriers are assessed, 18% meet the WHO criteria for serrated polyposis." (PMID 21660283, 2011). "Later research has identified other inherited variants such as MUTYH (MYH) polyposis and Hyperplastic Polyposis Syndrome." (PMID 19424478, 2008). "However, rare cases of serrated polyposis are reported where KRAS mutations predominate, and current evidence suggests that, in at least some of these patients, biallelic germline mutation of MUTYH may be responsible." (PMID 21660283, 2011).
breast and ovarian cancer (3 papers, 2022 to 2026). "The pathogenic mutations in genes such as MUTYH, FANCD2, NBN, PALB2, and BRCA1 are associated with hereditary breast and ovarian cancer syndrome, an autosomal dominant disorder typically manifesting around age 30 and above." (PMID 41229399, 2025).
glioblastoma (3 papers, 2020 to 2026). The most malignant astrocytic tumor (WHO grade IV).
intestinal tumors (3 papers, 2015 to 2021). "In murine studies, MUTYH-deficient mice were more susceptible to spontaneous tumors and oxidative stress-induced intestinal tumors." (PMID 26273655, 2015).
sarcoma (3 papers, 2024 to 2025). A usually aggressive malignant neoplasm of the soft tissue or bone. "The next most frequently mutated genes included CHEK2 (1.4%), ATM (1.2%), and MUTYH (1.2%), with the remaining DDR pathway genes altered in less than 1% of all sarcomas." (PMID 40563612, 2025).
thyroid cancer (3 papers, 2018 to 2024). "In the family #3, the index had had thyroid cancer preceding MM and carried P variants in POT1, CHEK2, and MUTYH but the father with MM (#3_I.1) shared only the CHEK2 and MUTYH variants." (PMID 36467798, 2022).
astrocytoma (2 papers, 2023 to 2025). "In this study, we detected MUTYH germline mutations in two young adults with high-grade astrocytoma, IDH mutant." (PMID 40469416, 2025).
cervical carcinoma (2 papers, 2019 to 2025). A carcinoma arising from either the exocervical squamous epithelium or the endocervical glandular epithelium. "Accordingly, we have designed a correlation study to determine potential associations between MUTYH Gln324His and cervical carcinoma in a Chinese population." (PMID 31027119, 2019). "However, all carriers in our sequencing study were heterozygous only, and larger studies will be needed to clarify whether MUTYH gene variants contribute to cervical cancer susceptibility." (PMID 39440754, 2025).
endometrial tumor (2 papers, 2021 to 2022). "Tumor mutational signatures provided evidence that germline variation in BRCA1, PALB2, RAD51C, MUTYH and NTHL1 can be (but is not always) associated with tumor mutational signatures consistent with a functional role of these genes in endometrial tumor development." (PMID 33917078, 2021).
iron overload (2 papers, 2021 to 2022). "However, not only the role of monoallelic MUTYH variants, but also the role of other repair enzymes for oxidative DNA damage in hepatocarcinogenesis in NASH patients with iron overload must be evaluated in large cohorts." (PMID 33574380, 2021).
kidney cancer (2 papers, 2022 to 2023). Primary or metastatic malignant neoplasm involving the kidney. "Similarly, MUTYH germline mutations have also been reported in many cancers, including kidney cancer." (PMID 36451132, 2022).
malignant brain tumors (2 papers, 2020 to 2021). "So far, MUTYH mutations are infrequent and have been shown in pediatric patients to increase risk of malignant brain tumors." (PMID 33639927, 2021).
memory impairment (2 papers, 2021 to 2023). "MUTYH deficiency improved memory impairment in AppNL-G-F/NL-G-F mice, accompanied by reduced microgliosis." (PMID 34970419, 2021). "We also found that MUTYH deficiency ameliorates impaired neurogenesis in the hippocampus, thus improving memory impairment." (PMID 34970419, 2021). "Importantly, we found that MUTYH deficiency apparently ameliorates only the memory impairment in six-month-old AppNL-G-F/NL-G-F mice; however, the differences observed in the findings of the open-field test and spontaneous locomotor activity in the home cage were not altered." (PMID 34970419, 2021). "Thus, we concluded that MUTYH actively contributes to microglial activation in the early phase of AD pathology, thereby affecting memory impairment." (PMID 34970419, 2021). "MUTYH, expressed in the hippocampus of AD and non-AD patients, induced microglial activation with poor neurogenesis, contributing to memory impairment." (PMID 36831315, 2023).
meningioma (2 papers, 2014 to 2023). A generally slow growing tumor attached to the dura mater. "In this regard, SNPs in the C variant of SOD3 (superoxide dismutase 3), GSTT1 (glutathione S-transferase theta 1), and MUTYH (Muty homolog) have been found to be associated with meningioma risk." (PMID 25003081, 2014). "Regarding HLA class II, 26 antigens were exclusively identified in the peptidome of meningiomas, with MAGEA10, MUTYH, and CABYR being the most frequent (6–15% positive tumors)." (PMID 37368072, 2023).
non-alcoholic steatohepatitis (2 papers, 2021 to 2023). "MUTYH has been shown to be possibly associated with hepatocarcinogenesis in nonalcoholic steatohepatitis in a mouse model." (PMID 37923899, 2023).
pilomatricomas (2 papers, 2009 to 2017). "Of note, multiple pilomatricomas were also reported in two siblings with MAP due to a homozygous truncating MUTYH mutation." (PMID 27573199, 2017).
prostate adenocarcinoma (2 papers, 2017 to 2024). "A recent report identified that heterozygous germline pLOF MUTYH mutations were observed twice as frequently in The Cancer Genome Atlas prostate adenocarcinoma cohort than in gnomAD cancer–free individuals; however, population stratification between these disparate cohorts cannot be discounted." (PMID 38458890, 2024).
pulmonary fibrosis (2 papers, 2020). Chronic progressive interstitial lung disorder characterized by the replacement of the lung tissue by connective tissue, leading to progressive dyspnea, respiratory failure, or right heart failure. "In summary, we demonstrated that MUTYH deficiency was associated with attenuated pulmonary fibrosis in BLM-induced mice." (PMID 33149810, 2020). "We used Mutyh knockout mice and a bleomycin-induced pulmonary fibrosis model to test the effect of MUTYH deficiency on lesion progression." (PMID 33149810, 2020). "The current study compared bleomycin-induced pulmonary fibrosis between Mutyh−/− and wild-type mice and demonstrated that MUTYH deficiency resulted in an attenuated fibrosis phenotype due to the alleviation of SSB accumulation in genomic DNA and reduced epithelial cell apoptosis." (PMID 33149810, 2020).
rectal cancer (2 papers, 2012 to 2016). A primary or metastatic malignant neoplasm that affects the rectum. "We found only 1 case with biallelic germline mutations in the MUTYH gene (p.Y176C;p.W472S) in a 29-year-old female with no family history and a MSS rectal cancer." (PMID 23049789, 2012).
retinal degeneration (2 papers, 2020 to 2021). Degeneration of the retina. "To further determine the mechanisms by which oxidative DNA damage promotes retinal degeneration, we employed rd10 mice to assess the function of MUTYH, which excises adenine mispaired with 8-oxoG." (PMID 32998461, 2020).
rheumatoid arthritis (2 papers, 2015 to 2017). A chronic, systemic autoimmune disorder characterized by inflammation in the synovial membranes and articular surfaces. "Here, we not only reporting the characterization of a SNP and potential copy number variation of MUTYH in rheumatoid arthritis patients, but also the MUTYH protein levels in RA patient’s serum." (PMID 28173856, 2017).
Serous carcinoma (2 papers, 2021 to 2023).
skin cancer (2 papers, 2022 to 2025). "These cases may suggest a role for early skin cancer screening in patients with known MUTYH mutations." (PMID 40290801, 2025).
small intestinal tumour (2 papers, 2015 to 2024). "Less frequently, monoallelic MUTYH variants have also been detected in other types of cancer, such as gastric, lung, liver, biliary and small intestine tumors." (PMID 38790183, 2024).
squamous cell carcinoma (2 papers, 2009 to 2015). A carcinoma arising from squamous epithelial cells. "The MUTYH His/His genotype also show a borderline significant risk for both adenocarcinoma and squamous cell carcinoma." (PMID 19161591, 2009).
triple-negative breast carcinoma (2 papers, 2016 to 2025). An invasive breast carcinoma which is negative for expression of estrogen receptor (ER), progesterone receptor (PR), and human epidermal growth factor receptor 2 (HER2). "The RAD51C c.905-2A>G is a splice acceptor variant, considered to be likely pathogenic, and it was confirmed in a triple-negative breast cancer patient who also had a VUS in the MUTYH gene (c.536A>G)." (PMID 40508121, 2025).
tumor syndrome (2 papers, 2024). "“MUTYH-associated tumor syndrome,” an alternative to MAP, has been proposed to better represent the broad phenotypic range associated with pathogenic MUTYH variants." (PMID 40225933, 2024).
-syndromic (1 paper, 2018). "This raises the question of whether MUTYH variants, especially the Tyr179Cys variant, may be associated with MBC risk only, or with the risk of familial or multi-syndromic diseases, including MBC." (PMID 30564557, 2018).
acute kidney injury (1 paper, 2025). Sudden and sustained deterioration of the kidney function characterized by decreased glomerular filtration rate, increased serum creatinine or oliguria. "MutY homolog (MUTYH) protein levels are significantly decreased in the kidneys of acute kidney injury (AKI) patients." (PMID 39921445, 2025). "The role of MUTYH, a DNA repair glycosylase in the pathogenesis of acute kidney injury (AKI) is unclear." (PMID 39921445, 2025).
adrenal tumours (1 paper, 2024). "More data on adrenal tumours in classic FAP patients with non-pathogenic APC variants is needed, like in those with MUTYH and HTHL1 variants." (PMID 39227904, 2024).